ENSG00000217631 (zinc finger pseudogene)
Gene: Processed pseudogene on chromosome 6 (49,273,600 to 49,273,794, forward strand). Ensembl gene ENSG00000217631.
Diseases named in the same sentence as ENSG00000217631 in open-access papers:
ENSG00000217631 is named in the same sentence as 1 disease in open-access papers, as found by Europe PMC text mining. Sharing a sentence is not in itself a finding about the gene and the disease.
ENSG00000217631 shares sentences with these, for which no sentence is quoted: myopia (1 paper).